TPX2 (TPX2 microtubule nucleation factor)
Diseases named in the same sentence as TPX2 in open-access papers (continued):
Sharing a sentence is not in itself a finding about the gene and the disease.
colon carcinoma (continued). "Together, these data suggest that downregulation of TPX2 inhibits Akt activation, and Akt activation is an important step in the TPX2-induced proliferation of colon cancer cells." (PMID 24341487, 2013). "As TPX2 is linked to the advanced clinical stage and poorer MFS of colon cancer patients, we then wanted to determine the possible role of TPX2 on cell migration and invasion activity in vitro." (PMID 24341487, 2013). "We also assessed the effect of TPX2 depletion on tumor invasion and demonstrated that disruption of endogenous TPX2 expression also attenuated cell invasive potential in colon cancer cells." (PMID 24341487, 2013). "The proportion of patients who developed metastasis from primary colon cancer after radical colectomy differed substantially between the TPX2-positive and TPX2-negative group (left)." (PMID 24341487, 2013). "Consistent with this, suppression of TPX2 expression inhibited proliferation and tumorigenicity of colon cancer cells both in vitro and in vivo." (PMID 24341487, 2013). "We demonstrate that AURKA and TPX2 are frequently amplified in cell lines from colon cancer of the chromosome instability (CIN) phenotype." (PMID 19259408, 2008). "Conversely, TPX2 downregulation could impede colon cancer and glioma cell proliferation and migration through PI3K/AKT/mTOR pathways." (PMID 38315450, 2024). "Overexpression of TPX2 has been observed in lung cancer, hepatic cancer, colon cancer." (PMID 32285914, 2020). "Additionally, TPX2 was verified as a target gene of microRNA-491 in esophageal cancer and played a critical role in cancer cell invasion in both esophageal and colon cancer." (PMID 28562334, 2017). "Furthermore, interfering with TPX2 in colon cancer cell lines decreased cell proliferation and also affected cell migration and invasion as well as expression of the metalloproteinase MMP-2." (PMID 25368990, 2014). "TPX2 expression was analyzed in human colon cancer cell lines and tumor samples." (PMID 24341487, 2013). "Our data revealed that depletion of TPX2 could suppress colon cancer cell migration and invasion in vitro." (PMID 24341487, 2013). "The impact of TPX2 on proliferation of colon cancer cells was evaluated by knockdown of TPX2." (PMID 24341487, 2013). "Collectively, these data indicate that TPX2 may be involved in colon cancer carcinogenesis and metastasis." (PMID 24341487, 2013). "The results indicate a critical role of TPX2 in the metastasis of colon cancer." (PMID 24341487, 2013). "Moreover, silencing of TPX2 reduced the tumorigenicity of colon cancer cells both in vitro and in vivo, implicating TPX2 as an oncogenic protein in the development and progression of colon cancer." (PMID 24341487, 2013). "In survival analyses, patients with TPX2 overexpression had worse overall survival and metastasis free survival, suggesting that deregulation of TPX2 may contribute to the metastasis of colon cancer." (PMID 24341487, 2013). "In our study, we found that TPX2 was a potential marker involved in tumorgenesis of colon cancer." (PMID 24341487, 2013). "To confirm whether TPX2 induced proliferation of colon cancer cells through the Akt pathway, we overexpressed TPX2 in SW480, which is a lower grade colon cancer cell line, then treated with a phosphoinositide 3-kinase (PI3K) inhibitor LY294002." (PMID 24341487, 2013). "We observed that the expression levels of TPX2 were closely correlated with the T classification (P = 0.008), lymph node involvement (P = 0.001), distant metastasis (P = 0.048), and clinical stage (P = 0.004) in colon cancer patients." (PMID 24341487, 2013). "TPX2 was markedly upregulated in colon cancer cells and tissues." (PMID 24341487, 2013). "In the present study, we explored whether TPX2 contributed to migration and invasion of colon cancer cells in vitro." (PMID 24341487, 2013). "However, little work has been done to explore the role of TPX2 in colon cancer." (PMID 24341487, 2013).
colon carcinoma (continued). "Since TPX2 has multiple roles in the progression of colon cancer, including regulation of proliferation, invasion, and metastasis of colon cancer cells, the frequent upregulation of TPX2 in human colon cancers highlights its importance as a novel therapeutic target in the treatment of colon cancer." (PMID 24341487, 2013). "TPX2 activates PI3K/Akt pathway and upregulates matrix metalloproteinases (MMP) family members in colon cancer." (PMID 30254986, 2018). "Inhibition of TPX2 expression inactivates the PI3K/Akt signaling pathway and reduces tumorigenicity of colon cancer cells." (PMID 24341487, 2013). "Indeed, several research groups have reported the importance of Chr20 amplification in colon cancer, and attributed such effect to the location of multiple oncogenes such as BCL2L1, AURKA, TPX2, and SRC on this chromosome." (PMID 38593144, 2024). "We found that TPX2 was dramatically upregulated in primary colon cancer (61.1%), but it was either only detected minimally, or not at all (98%) in adjacent normal colonic tissue." (PMID 24341487, 2013). "And the protein expression level of TPX2 was also higher in the colon cancer cell lines but not so markedly as its mRNA expression level (Figure 1A2)." (PMID 24341487, 2013). "Real-time PCR analyses revealed that mRNA expression level of TPX2 was markedly higher in all colon cancer cell lines than in non-malignant human NCM460 colonic cell line (Figure 1A1)." (PMID 24341487, 2013). "Importantly, TPX2 acts as an oncogenic protein and upregulates the expression of matrix metalloproteases (MMPs) through activation of the phosphatidylinositol 3-kinase (PI3K)/Akt signaling pathway in colon cancer." (PMID 25302620, 2014). "Furthermore, comparative analysis showed that the mRNA and protein levels of TPX2 were differentially upregulated in all 4 colon cancer samples compared to the matched adjacent non-tumor tissues (Figure 1B1, B2), suggesting that TPX2 expression is upregulated in colon cancer." (PMID 24341487, 2013). "However, no attempt has been made to investigate the expression of TPX2 in human colon cancer." (PMID 24341487, 2013).
gastric cancer (19 papers, 2016 to 2026). A primary or metastatic malignant neoplasm involving the stomach. "The overexpression of CCNB1 and TPX2 have been demonstrated to be associated with poor survival in Gc." (PMID 30174615, 2018). "Our results indicated that high TPX2 expression was associated with tumor progression and poor survival in gastric cancer." (PMID 28069036, 2017). "We found that high TPX2 expression was associated with tumor progression and poor survival in gastric cancer patients." (PMID 28069036, 2017). "The associations of TPX2 expression with the clinicopathological features were analyzed, and the prognosis of gastric carcinoma patients was evaluated." (PMID 27777511, 2016). "In this study, we sought to investigate the expression of TPX2 and its associated prognostic significance in gastric carcinoma." (PMID 27777511, 2016). "TPX2 is a microtubule-associated protein that activates the cell cycle kinase protein Aurora-A, which then plays an vital role in spindle formation in mitosis, and high TPX2 expression is associated with tumor progression and low survival in gastric cancer." (PMID 39371335, 2024). "Therefore, in this study, we evaluated the expression of TPX2 in surgically resected specimens of gastric cancer and analyzed the association between TPX2 expression, clinicopathological factors, and survival." (PMID 28069036, 2017). "TPX2 is up-regulated in gastric carcinoma and is associated with old age and tumor T stage." (PMID 27777511, 2016). "Moreover, high TPX2 expression was associated with poor survival in gastric cancer and NSCLC." (PMID 30305064, 2018). "An inverse relationship was observed between NKX6.3 expression and the levels of AurkA and TPX2 in human gastric cancer tissues." (PMID 39833908, 2025). "Expression of the TPX2 protein was assessed by immunohistochemical staining of gastric cancer tissue samples from 290 patients." (PMID 28069036, 2017). "In this study, we used a large set of surgically resected gastric cancer tissue samples to assess the expression of TPX2 at the protein level." (PMID 28069036, 2017). "The mRNA levels of TPX2 were significantly higher in gastric cancer tissues than in matched adjacent normal tissues (p = 0.004)." (PMID 28069036, 2017). "Nevertheless, there have been few studies that have reported investigation of the expression of TPX2 in gastric cancer." (PMID 28069036, 2017). "Initially, we assayed TPX2 mRNA levels in a retrospective cohort of 19 gastric cancer tissues and matched adjacent normal tissues using qRT-PCR." (PMID 28069036, 2017). "In this study, we evaluated TPX2 expression and investigated its correlations with gastric cancer clinicopathological features and prognosis." (PMID 28069036, 2017). "In this cohort, the median TPX2 mRNA level was significantly higher in gastric cancer tissues than in matched adjacent normal tissues (p = 0.004)." (PMID 28069036, 2017). "We further analyzed the relationship between the expression of TPX2 and the clinical characteristics of patients with gastric carcinoma." (PMID 27777511, 2016). "Further studies are warranted to elucidate the molecular mechanism of TPX2 in the development and progression of gastric carcinoma." (PMID 27777511, 2016). "Based on previous studies, we investigated the expression of TPX2 in gastric carcinoma and its prognostic value in predicting OS following curative resection in the present study." (PMID 27777511, 2016). "The results showed that the expression of TPX2 mRNA was significantly higher in gastric carcinoma than in the adjacent normal tissues in 20 paired samples." (PMID 27777511, 2016). "The main objective of this study was to investigate the expression level of targeting protein for Xenopus kinesin-like protein 2 (TPX2) and its clinical significance in human gastric carcinoma." (PMID 27777511, 2016).
gastric cancer (continued). "In the meta-analysis, TPX2 expression was significantly higher in the gastric carcinoma tissues than in the corresponding normal tissues (median rank of 187.5, P value of 8.51E−8)." (PMID 27777511, 2016). "TPX2 expression in samples of human gastric cancer has been investigated in one previous study." (PMID 28069036, 2017). "Our results indicated that high expression of TPX2 may play a critical role in tumor progression, metastasis, and survival in gastric cancer." (PMID 28069036, 2017). "However, in the Oncomine database, high levels of TPX2 mRNA and copy number gain of the TPX2 gene are shown in some datasets of human gastric cancers." (PMID 28069036, 2017). "Moreover, they further reported that TPX2-siRNA suppressed tumor cell epithelial-mesenchymal transition in gastric cancer cell lines." (PMID 28069036, 2017). "In addition, IHC analysis showed that TPX2 was overexpressed in 78 of 106 (73.58 %) gastric carcinoma specimens." (PMID 27777511, 2016). "Multivariate analysis revealed that TPX2 expression, age, tumor size, and N stage may be independent prognostic indicators of OS in gastric carcinoma patients." (PMID 27777511, 2016). "TPX2 and MKI67 have been recognized as prominent genes in gastric cancer, with elevated TPX2 expression linked to tumor progression and poor survival outcomes, suggesting its potential role as a biomarker for adverse prognosis or a target for future therapeutic strategies in gastric cancer." (PMID 40445003, 2025). "Moreover, TPX2 stimulates gastric cancer cell migrative and invasive capacity." (PMID 35395834, 2022). "TPX2 may thus play an important role in tumor progression in gastric cancer." (PMID 28069036, 2017). "TPX2 may serve as a good prognostic indicator in patients with gastric carcinoma." (PMID 27777511, 2016). "We highlighted genes, including TPX2, MKI67, EXO1, and CTHRC1, as potential biomarkers for early diagnosis, prognostic evaluation, and therapeutic targeting in gastric cancer." (PMID 40445003, 2025). "Previous studies have reported the differential expression of the genes we identified in gastric cancer, but few studies have reported the differential expression of AURKB, CCNA2, PLK1, TPX2, and CDK1 in gastric cancer." (PMID 37238607, 2023). "A former study has reported that there is a positive correlation between TPX2 up-regulation and lymph node metastasis, TNM stage, as well as poor prognosis of patients in cancers including cholangiocarcinoma, gastric cancer, and lung adenocarcinoma." (PMID 31417870, 2019). "In addition, KIF4A overexpression can promote endometrial cancer progression by inhibiting TPX2 protein degradation, while KIF4A expression is reduced in gastric cancer, multiple myeloma, and acute myeloid leukemia." (PMID 38937742, 2024). "Survival analysis showed a clear negative correlation between the TPX2 protein expression level and OS of patients with gastric cancer (P = 0.001)." (PMID 27777511, 2016). "Our results clearly showed that TPX2 was up-regulated at both the mRNA and protein levels in twenty gastric carcinoma tissues compared with matched non-tumor gastric tissues." (PMID 27777511, 2016). "Western blotting analysis revealed that TPX2 protein was differentially increased in 17 of 20 specimens from primary human gastric carcinoma tissues compared with those from adjacent non-tumor tissues." (PMID 27777511, 2016). "Western blotting analysis revealed that TPX2 protein was differentially increased in 17 of 20 primary human gastric carcinoma tissue specimens compared with the adjacent non-tumor tissues, indicating that TPX2 is up-regulated in gastric carcinoma." (PMID 27777511, 2016). "The difference in the expression of TPX2 between gastric carcinoma and non-tumor tissues indicates that TPX2 may be a key regulator in tumorigenesis and the prognosis of gastric carcinoma." (PMID 27777511, 2016).
gastric cancer (continued). "However, no report concerning TPX2 expression and its prognostic value in gastric carcinoma exists in the literature." (PMID 27777511, 2016).
pancreatic cancer (19 papers, 2012 to 2026). "TPX2 is known as a cancer-related gene that is involved in the normal assembly of mitotic spindles and microtubules during apoptosis and is also associated with unfavorable prognosis in lung cancer, liver cancer, pancreatic cancer, and renal cancer." (PMID 34616422, 2021). "In patient-derived xenograft models of pancreatic cancer, reduced TPX2 expression correlates with increased sensitivity to PARP inhibitor (PARPi) treatment." (PMID 40362354, 2025). "Emerging publications have reported that TPX2 overexpression is closely related to the development of various malignant tumors, including cervical cancer, esophageal squamous cell carcinoma and pancreatic cancer." (PMID 36204642, 2022). "In summary, this study demonstrated that TPX2 silencing has a novel therapeutic potential in pancreatic cancer." (PMID 25914189, 2015). "In this study, we first examined the expression of TPX2 in human pancreatic cancer specimens, and normal pancreatic tissues." (PMID 25914189, 2015). "As was expected, TPX2 siRNA effectively suppressed the proliferation of pancreatic cancer cell cultures." (PMID 25914189, 2015). "The expression of TPX2 mRNA was significantly higher in pancreatic cancer tissues (12.4 ± 2.5) than in normal tissues (1 ± 0.7) (P < 0.001)." (PMID 25914189, 2015). "Real-time RT-PCR demonstrated that the expression of the TPX2 gene was strongly knocked down by TPX2 -siRNAs in the three selected pancreatic cancer cell lines, KLM1, KP4, and Panc1." (PMID 25914189, 2015). "With regard to pancreatic cancer, an increased TPX2 copy number has been reported in pancreatic cancer cell lines and surgically resected tumor samples analyzed by array comparative genomic hybridization." (PMID 25914189, 2015). "Further investigation is necessary to elucidate the precise mechanism of TPX2 and its association with IGFBP-3 to establish a novel molecular targeting treatment for pancreatic cancer." (PMID 25914189, 2015). "In this study, we verified the overexpression of TPX2 in both surgically resected specimens of pancreatic cancer and multiple pancreatic cancer cell lines." (PMID 25914189, 2015). "In this study, in accordance with the previous studies, we found an overexpression of TPX2 in both surgically resected specimens and eight different pancreatic cancer cell lines." (PMID 25914189, 2015). "Subsequently, we found that TPX2 siRNA effectively suppressed the proliferation of pancreatic cancer cells in culture, and the direct injection of TPX2 siRNA into subcutaneously implanted pancreatic cancer cells in nude mice revealed antiproliferative effects." (PMID 25914189, 2015). "The oncogenic role of TPX2 in pancreatic cancer development has been demonstrated in previous studies." (PMID 22363658, 2012). "Furthermore, inhibiting TPX2 S634 phosphorylation with a cell-penetrating peptide enhances pancreatic cancer cell responsiveness to PARPi." (PMID 40362354, 2025). "Subsequently, the mechanistic role of TPX2 in cancer progression and angiogenesis was investigated to determine whether TPX2 siRNA has therapeutic potential as a molecular targeting drug for pancreatic cancer." (PMID 25914189, 2015). "TPX2 siRNA also inhibited cell proliferation in several pancreatic cancer cell cultures." (PMID 25914189, 2015). "The results also implied that the antiangiogenic effect of TPX2 siRNA in pancreatic cancer cells may be partly explained by the upregulation of IGFBP-3." (PMID 25914189, 2015). "Based on the observation of TPX2 overexpression in pancreatic cancer tissues and cell lines, we hypothesized that a suppression of TPX2 expression may have an antiproliferative effect on pancreatic cancer cells." (PMID 25914189, 2015). "Moreover, increased expression of IGFBP-3 upon treatment with TPX2 siRNA was observed in three pancreatic cancer cell lines such as KLM1, KP4, and Panc1 by Western blot analysis and real-time RT-PCR." (PMID 25914189, 2015).